MCL1 (MCL1 apoptosis regulator, BCL2 family member)
Diseases named in the same sentence as MCL1 in open-access papers (continued):
Sharing a sentence is not in itself a finding about the gene and the disease.
cancer (continued). "In this review, we synthesize recent advances elucidating how Mcl1 integrates epithelial cell-fate decisions, immune signaling and tumor evolution across the IBD-cancer continuum." (PMID 42194042, 2026). "In a large-scale RNAi screening aimed at understanding cancer dependencies and synthetic lethal relationships, the top correlates of WSB2 co-essentiality were found to be MCL-1, BCL-2, and MARCH5, while the most strongly anti-correlated gene with WSB2 was BAX." (PMID 40699886, 2025). "Increased expression of BCL2 family members including MCL1, BCL2L1 (BCL-xL), BCL2A1 (BFL1), and BCL2 itself drives resistance to single-agent venetoclax in various cancers." (PMID 39894894, 2025). "Previous investigations have shown a close interaction between MCL-1 and FAO enzymes in cancer cells, and mouse studies have also established the importance of FAO for maintenance of embryonic neurodevelopment and adult NSCs26,38,43." (PMID 41427398, 2025). "However, as methylation of DNA is considered a stable change in DNA that is less susceptible to treatment-induced alterations compared with gene expression, BCL2L1 methylation at cg00300298 may be a better predictor of MCL1 inhibitor response in pediatric cancer." (PMID 39846250, 2025). "Among the SCF complex substrates, the anti-apoptotic proteins MCL1 and HAX1 have been shown to play critical roles in promoting cancer cell survival and therapeutic resistance." (PMID 41154579, 2025). "This is in line with other studies that show that simultaneously targeting Mcl-1 and c-FLIP can efficiently eliminate cancer cells." (PMID 39753884, 2025). "Work from the Opferman and Walensky groups revealed an unexpected link between MCL-1 and FAO in cancer cells." (PMID 41427398, 2025). "In many cancers, SYK promotes cell survival by activating the PI3K/AKT signaling pathway, which stabilizes anti-apoptotic proteins such as MCL-1, BCL-XL, and XIAP." (PMID 40507977, 2025). "Therefore, the current study could/ consist of the basis for future both in vitro as well as in vivo experiments, ii/ determine the potential new strategy, and in conclusion, iii/give the future directions in the treatment of cancers for which Mcl-1 protein consists of important molecular targets." (PMID 40892149, 2025). "Many cancers exploit anti-apoptotic BCL-2 proteins—like BCL-2, BCL-XL, and MCL-1—to evade cell death." (PMID 40204952, 2025). "These small molecules antagonize anti-apoptotic proteins such as BCL-2, MCL-1, or BCL-XL, on which cancer cells depend for their survival." (PMID 40365276, 2025). "Therefore, the current study could (i) serve as the basis for future both in vitro as well as in vivo experiments, (ii) help determine the potential new strategy, and in conclusion, (iii) provide future directions in the treatment of cancers for which Mcl-1 protein is an important molecular target." (PMID 40807447, 2025). "The ABCG2, CYP3A4, MCL1, and MLH1 genes are overexpressed in various cancers and are involved in chemoresistance to multiple drugs." (PMID 39931465, 2025). "In this study, we identified the anti-apoptotic MCL-1 adaptation in response to ALK inhibitors in cell lines and patient-derived cancer cells." (PMID 40113795, 2025). "However, if cancer cells are MCL-1 primed, to a greater or lesser degree, then the patients harboring those “primed to adapt” cancer cells might be steered to a treatment that could target the MCL-1:BIM complexes cells even before relapse from BCL-2:BIM targeting treatment." (PMID 40507334, 2025). "The current study is a continuation of our previous study concerning the role of Mcl-1 protein in MOXI cytotoxic and proapoptotic effects toward TNBC cancer cells." (PMID 40892149, 2025). "The downstream targets of STAT3 include anti-apoptotic genes (BCL-2, BCL-XL, MCL-1), cell survival pathway genes (Cyclin-D1, Survivin), drug efflux (MDR1), and maintenance genes of cancer stem cells (CD133)." (PMID 40149331, 2025).
cancer (continued). "KS18 also demonstrated greater cancer cell death than the Bcl-2/Bcl-xL inhibitors venetoclax and ABT-737, further highlighting Mcl-1 as a dominant survival factor in resistant MM." (PMID 41149606, 2025). "In the baseline samples, high expression of anti-apoptotic genes MCL1 and BCL2A1 in MDSCs from patients with cancer was observed compared with other cell types." (PMID 40762981, 2025). "In cancer cells, YY1’s impact extends to the regulation of key anti-apoptotic genes, including Bcl-2, Bcl-xl, Mcl-1, and survivin, known for their involvement in therapeutic resistance and cancer progression." (PMID 38893192, 2024). "K-means clustering of >600 000 cancer cells and cell level intensities of APAF1, procaspase-9, procaspase-3, XIAP, SMAC, BAX, BAK, BCL2, BCL-XL, MCL-1, procaspase-8, BID, FADD, FLIP, RIP3 and CIAP1 identified distinct cell cluster profiles." (PMID 39886119, 2024). "MCL1 inhibitors are designed to mimic BH3 domains and occupy the BH3-domain binding groove in MCL1, in this way blocking MCL1 interaction with the BH3 domains of other proteins and inducing cancer cell death." (PMID 39802137, 2024). "Mcl-1 overexpression enhanced mitochondrial fusion and stabilized the mitochondrial structure, providing cytoprotective effects in IMQ-treated cancer cells." (PMID 39272918, 2024). "In this study, we found that IMQ-induced production of ROS and mitochondrial superoxide was significantly abolished in Mcl-1-overexpressing BCC and AGS cancer cells." (PMID 39272918, 2024). "The combination of the AKT inhibitor capivasertib (AZD5363) with the MCL1 inhibitor AZD5991 was one of the most selective combinations, active in only 2 of 41 cancer types." (PMID 38456804, 2024). "It has become clear that MCL-1 has a binding profile different from BCL-2/BCL-XL/BCL-w, and neutralising MCL-1 kills many cancer cells efficiently." (PMID 39285161, 2024). "A structure-based computational study against the HeLa cancer cell related protein targets (BCL-2 (4MAN), AKT-1 (4GV1), MCL-1 (5FDO), and BRAF (5VAM)) was used to determine the most potent biomarker." (PMID 40190673, 2024). "A high MCL-1 expression also correlates with an increased M1 and M2 macrophage infiltration in CRC tumors, affecting cancer cell proliferation and EMT." (PMID 39199569, 2024). "For example, CDK9 inhibition is known to suppress highly expressed genes involved in cancer cell proliferation, metastasis, and treatment resistance, including MYC and MCL-1." (PMID 38172923, 2024). "The proposed dysregulated resistant circuit involving NF-κB, YY1, Mcl-1, and DR5, modified by Obatoclax, offers insights into potential therapeutic strategies for overcoming resistance in GBM cancer cells." (PMID 38893192, 2024). "Therefore, Mcl-1 may stabilize mitochondrial homeostasis to against IMQ treatment in cancer cells." (PMID 39272918, 2024). "These marker genes play diverse roles in cancer, such as promoting growth and proliferation (MYC, HIF1A, ATM), inhibiting apoptosis (MCL1, BIRC3, BCL2) and facilitating invasion (CXCR4, CD55)." (PMID 38982317, 2024). "Numerous studies have demonstrated that elevated levels of pro-survival proteins, including BCL-xL, MCL-1, and BCL-2, are frequently observed in cancers and contribute to drug resistance." (PMID 38898061, 2024). "The strategic inhibition of MCL-1 using peptides like SAHBD has been shown to promote caspase-dependent apoptosis, particularly in cancer cells that rely on MCL-1 for survival." (PMID 39795861, 2024). "The abnormal overexpression of MCL1, BCL2, and related antiapoptotic BH3 family genes helps to stabilize mitochondria, promoting tumorigenesis and drug resistance in various cancers." (PMID 39590121, 2024). "A similarly important example is the targeting of MCL-1, an anti-apoptotic member of the BCL-2 family that often mediates chemoresistance in various cancers." (PMID 39795861, 2024).
cancer (continued). "We further revealed that inhibitors targeting the Src, Mcl‐1, STAT3, BRD4, p300, PLK1, or class I HDACs significantly enhanced CDK9i‐induced cell death in various KRAS‐mutant cancers." (PMID 39254172, 2024). "Considering STAT3’s function in promoting the transcription of pro-survival genes such as Mcl-1, this approach indicates that KS18 can proficiently interfere with a principal pathway that sustains elevated Mcl-1 levels in resistant cancer cells." (PMID 39411073, 2024). "We and several others have recently shown that short-term inhibition of CDK9 depletes short-lived transcripts and labile proteins such as MCL1 and MYC to promote cancer cell death." (PMID 38371625, 2024). "In this study, we demonstrated that Mcl-1 overexpression induced resistance to IMQ-induced apoptosis and reduced both IMQ-induced ROS generation and oxidative stress in cancer cells." (PMID 39272918, 2024). "As key regulators of apoptosis, MCL-1 and BCL-2 are survival factors and thus considered ideal cancer targets." (PMID 38008859, 2024). "In previous studies focusing on other cancer types, responsiveness to MCL-1 inhibitors tended to mirror MCL-1 levels and inversely correlate with BCL-xL abundance." (PMID 39497108, 2024). "This study demonstrated that the overexpression of Mcl-1 or IL-6-induced Mcl-1 upregulation reversed mitochondrial dysfunction, mitochondrial fission, and mitophagy in IMQ-treated cancer cells and protected them from IMQ-induced apoptosis." (PMID 39272918, 2024). "Mcl-1 overexpression maintained mitochondrial function and integrity and prevented mitophagy in IMQ-treated cancer cells." (PMID 39272918, 2024). "Myeloid cell leukemia-1 (MCL1) is an anti-apoptotic member of the B-cell lymphoma 2 (BCL-2) family and plays a key role in cancer cell survival and resistance to therapy." (PMID 39802137, 2024). "Genes such as PARP1, NAMPT, AIMP2, MCL1, and TOMM20 exhibited widespread amplifications of CNVs in multiple cancers, while genes like RNF146, GPX4, ESR1, CUL4A, and PTEN showed widespread deletions." (PMID 38499384, 2024). "SRSF5 is reported to promote cancer development and progression by regulating the splicing of multiple genes, including ETS1, METTL14, Mcl-1, Cyclin L2, and CCAR1." (PMID 38263157, 2024). "In this study, we found that Mcl-1 mitigated IMQ-induced oxidative stress and consequently protected cancer cells from death via IMQ." (PMID 39272918, 2024). "Anti-apoptosis factors including MCL1, BCL2, BCLxL and BFL1 are crucial mediators of tumorigenesis and resistance to therapy in various cancers." (PMID 38371625, 2024). "MCL1 is a member of the BCL2 family of apoptosis regulators, which play a critical role in promoting cancer survival and drug resistance." (PMID 38371625, 2024). "MCL-1 is expressed at relatively high levels in many haematological malignancies, including MM and acute myeloid leukaemia (AML), as well as in cancers of the breast, pancreas, prostate, lung, and ovary." (PMID 36342579, 2023). "As the upregulation of MCL1 is common in TNBC, we sought to determine if these emerging inhibitors can be combined with neoadjuvant chemotherapies to improve the anti-cancer response." (PMID 37760451, 2023). "It has been demonstrated that CDK9 mediates apoptotic resistance via transcriptionally controlling the overexpression of anti-apoptotic proteins in cancer cells such as c-FLIP and Mcl-1." (PMID 36979907, 2023). "MCL-1 is a member of the antiapoptotic BCL2 family, and its significance in cancer is well understood." (PMID 37833817, 2023). "MCL-1 specific inhibitors MIK665, AMG 176, AZD5991 have advanced to phase I/II clinical trials for cancer therapies, some in conjunction with the BCL-2 inhibitor ABT-199 (rev in:)." (PMID 37864894, 2023). "Obatoclax was developed as a pan-BH3 mimetic to induce apoptosis of cancer cells by disrupting multiple interactions, including those between anti-apoptotic BCL2 family proteins (BCL2, BCLXL, and MCL1) and BAX and BAK interactions." (PMID 37759469, 2023).
cancer (continued). "As MARCH5 can regulate mitotic apoptosis in a MCL1-independent mechanism, it is possible that targeting MARCH5 can promote sensitivity to antimitotic treatments even in cancer cells overexpressing MCL1." (PMID 36329234, 2023). "Thousands of mRNAs are ELAVL1 targets, including factors fostering diverse cancer traits such as proliferation (cyclins A2, B1, D1, and E1), angiogenesis (HIF1a, PTGS2, and VEGFA), survival (BCL2 and MCL1), and invasion (MMP9 and SNAI1)." (PMID 37298909, 2023). "We demonstrate that dual inhibition of BCL2/XL and MCL1 is synergistic in 4 out of 5 tested HGSOC models, and that treatment efficacy is significantly enhanced by LbL NP‐mediated delivery to cancer cells in vitro." (PMID 36925689, 2023). "Thus, inhibition of MCL-1 expression or function may restore drug sensitivity in cancer cells." (PMID 38027013, 2023). "Several proteins from Bcl-2 family proteins, such as Mcl-1, NOXA, and Bad, have been shown to be involved in the reprogrammed metabolism in cancer cells." (PMID 37069941, 2023). "The apoptotic marker cleaved‐PARP exhibited substantial elevation, while the antiapoptotic protein MCL1, a BCL‐2 family member and a mitochondrial apoptosis inhibitor often overexpressed in cancers, showed a notable reduction." (PMID 38037549, 2023). "Results revealed a significant up-regulation of MCL1 and CCND1, and a significant down-regulation of IGF1R and PTEN in KIRC patients with varying cancer stages, races, genders, and age groups compared to normal controls." (PMID 37744271, 2023). "Overexpression of anti-apoptotic proteins of the BCL-2 family, such as BCL-2, BCL-xL and MCL-1, is frequently found in various cancers, including AML, thereby perturbing homeostasis of survival pathways and protecting cancer cells from death." (PMID 37726279, 2023). "A recent finding showed that induced myeloid leukemia cell differentiation protein (MCL-1)-driven cancer cells are sensitive to FAO inhibition, and genetic deletion of MCL-1 induces global downregulation of the FAO pathway." (PMID 37762231, 2023). "The most potent compound 2g inhibited cancer cell proliferation by blocking Rb phosphorylation and induced apoptosis via downregulation of CDK9 downstream proteins Mcl-1 and c-Myc in MIA PaCa-2 cells." (PMID 36656085, 2023). "Over-expression of ITGB1 in ccRCC strikingly reduced Mcl-1 expression, indicating that ITGB1 promotes cancer progression by modulating Mcl-1." (PMID 36969848, 2023). "Some cancers have been refractory towards ABT-199 treatment, and a proposed reason for this is increased MCL-1 expression." (PMID 37864894, 2023). "Most hematological malignancies are characterized by overexpression of certain cancer promoting genes, such as MYC, MCL1 and cyclin D1." (PMID 37552223, 2023). "Increasing evidences suggested that its family member, Myeloid Cell Leukemia 1 (MCL-1), owned its pro-survival activity in many cancers." (PMID 37470692, 2023). "It has been proven that persistent VTX exposure leads to the upregulation of different pro-survival Bcl-2 family members, such as BCL-XL, MCL-1, and BCL2-A1, which have been found to be overexpressed in many hematologic malignancies and other cancers." (PMID 38069030, 2023). "MiR-29a also plays a significant role in promoting apoptosis via several effectors including MCL-1, KDM5B, QKI-6, MMP2, and TNFR1 in various cancers." (PMID 37684602, 2023). "Hence, MCL1 maybe a potential indicator for cancer malignancy." (PMID 36937870, 2023). "When adenovirus-mediated RNAi technology was used to knockdown the expression of Mcl-1 in GC, CD44+ cancer stem cell (CSC)-like cells became sensitized to chemotherapeutic agents such as 5-fluorouracil (5-FU) and cisplatin (CDDP)." (PMID 36505792, 2022). "The over-activated STAT3 signaling in cancer cells induces target gene expression; these genes include cyclinD1 (promotes cell growth) and the BCL2 family member MCL-1 (reduces apoptosis)." (PMID 35810312, 2022).
cancer (continued). "However, the association between Mcl-1 and oral cavity, cancers is not clearly defined." (PMID 35524332, 2022). "Cancer cells can evade apoptosis via upregulating the expression levels of antiapoptotic proteins such as XIAP, Mcl-1, and Survivin." (PMID 35222445, 2022). "Overexpression of four top candidate genes (CD274 (PD-L1), MCL1, JUNB, and B3GNT2) conferred resistance in diverse cancer cell types and mouse xenografts." (PMID 35338135, 2022). "For effective anti-cancer therapy, BH3-mimetic drugs must counteract the pro-tumor functions of MCL-1 that occur in vivo." (PMID 35349392, 2022). "Together these findings indicate that chemotherapy-induced MCL1 translocation represents a novel resistance mechanism in CRC, while also exposing an inherent and targetable Bcl-xL co-dependency in these cancers." (PMID 35042842, 2022). "Together, these studies indicate that DDX5 acts as an upstream master regulator to control the expression of survivin, Mcl‐1, XIAP, cIAP2, c‐Myc and mKras, which are key oncogenic proteins involved in cancer development and malignant networks." (PMID 35604033, 2022). "Moreover, MCL1 antagonist Sabutoclax could increase cancer cell death in OSCC as well." (PMID 35769708, 2022). "Excessive NF-κB signaling in cancer cells can suppress apoptosis via inducing the expression of apoptosis inhibitors such as XIAP, Mcl-1, and Survivin." (PMID 35222445, 2022). "Importantly, suppression of DUBs upstream of MCL-1 is an attractive approach by which MCL-1 levels could be decreased in cancers, although the principal enzymes responsible for MCL-1 stabilization are highly cell-type specific and dependent on the wider proteomic profile of the target cell." (PMID 35349392, 2022). "Focal amplification peaks, including the well‐studied cancer‐driven gene MYC (8q.24.21) and several antiapoptotic genes (MCL1, HORMAD1, and ECM1 on 1q21.2), were identified in the high‐risk patients, along with a focal deletion peak at 13q14.2." (PMID 34894177, 2022). "The induced myeloid leukemia cell differentiation protein (MCL-1) gene is one of the key members of the BCL-2 family, and it is highly expressed in many cancers of the blood, such as lymphoma and leukemia." (PMID 36557960, 2022). "As observed in other cancers, THZ1 synergized with the Bcl‐2 inhibitor venetoclax most likely in part by suppressing MCL‐1." (PMID 35253392, 2022). "Cancer cells escape apoptosis by a variety of mechanisms, including increased production of pro-survival proteins (BCL2, BCLXL, or MCL1)." (PMID 35945614, 2022). "Increasing evidence from solid tumors suggests that several cancer cell types are dependent on more than one BCL2 family protein for survival and in particular, dual inhibition of MCL1 and BCL-XL is required to successfully facilitate apoptosis." (PMID 33803266, 2021). "Resistance to the inhibition of BCL2 was overcome by inhibiting MDM2; cancer cells can become resistant to BCL2 inhibition by increasing the production of other anti-apoptotic proteins, such as MCL-1." (PMID 35008180, 2021). "Previous reports have demonstrated that cancer cells harboring aberrant STAT3 activities elevate levels of anti-apoptotic proteins such as BCL2, BCL-xL, and myeloid cell leukemia 1 (MCL1)." (PMID 34268250, 2021). "A wide range of malignancies rely on MCL-1 for survival, and MCL-1 is one of the most frequently amplified genes in human cancer." (PMID 35008216, 2021). "These included four additional pro-survival members namely BCL-XL, BCL-W, MCL-1 and BFL-1, all of which have since been shown to contribute to the survival of various cancers." (PMID 33799592, 2021). "MCL-1, an anti-apoptotic member of the BCL-2 family proteins, is frequently overexpressed in a variety of cancers." (PMID 33106913, 2021). "Overall, almost all CRC lines share sensitivity in the nanomolar range to combined MCL-1 and BCL-XL targeting suggesting that this would be the preferred approach to target these cancers." (PMID 33917026, 2021).